SCD5 (stearoyl-CoA desaturase 5)
Diseases named in the same sentence as SCD5 in open-access papers (continued):
Sharing a sentence is not in itself a finding about the gene and the disease.
thymic carcinoma (1 paper, 2020). Thymic carcinoma (TC) is a type of thymic epithelial neoplasm characterized by a high malignant potential. "Next, to evaluate the involvement of LINC00174 and SCD5 in the control of lipids production in thymic carcinoma cells TC1889, we examined, by oil red assay, the amount of lipid droplets upon LINC00174 or SCD5 silencing." (PMID 33161413, 2020). "The ability of SCD5 to increase lipid droplets cell content in thymic carcinoma cells was also confirmed by overexpression experiments using an SCD5 expression vector." (PMID 33161413, 2020).
uveal melanoma (1 paper, 2021). A melanoma derived from melanocytes of the uveal tract. "While, SCD5 was also reported to be up-regulated in uveal melanoma, and high expression of SCD5 was related to poor prognosis." (PMID 33903614, 2021).
tumor (31 papers, 2013 to 2025). "Key genes, including CD36, FABP4, PLIN1, PLIN4, SCD5, and ACSLs, were consistently downregulated in tumor tissues, with further reductions observed in KRAS-mutated samples." (PMID 40860798, 2025). "In summary, our study shows that mRNA and protein levels of SCD5/fat-7 are substantially downregulated in VHL-deficient ccRCC tumor samples and ccRCC cells, as well as in C. elegans vhl-1 loss-of-function mutants." (PMID 36980176, 2023). "Changes in the expression and AS of human stearoyl-CoA desaturase-5 (SCD5) are promising specific tumor markers, although the transcript variants (TVs) of the gene have not yet been confirmed." (PMID 37047490, 2023). "In our model the SCD5-associated spreading reduction correlates with the diminished secretion in the tumor microenvironment of SPARC that is known to modify the extracellular matrix." (PMID 29484133, 2018). "In recent years, the results of high-throughput whole genome, transcriptome and microRNA sequencing data have directed attention to tumor-related changes in the expression level of SCD5; however, the underlying molecular mechanism of these alterations remains to be elucidated." (PMID 37047490, 2023). "The endogenous levels of SCD5 mRNA expression and protein levels were reduced in ccRCC tumor samples." (PMID 36980176, 2023). "Taken together, our data extend previous findings, suggesting that SCD5 plays a key role in tumor formation." (PMID 36980176, 2023). "The result of immunohistochemistry revealed that highly expressed SCD5 was found in breast normal tissues compared to tumor tissues, which was opposite to SCD1." (PMID 33903614, 2021). "At the same time, FADS3 expression in the peritumoral area negatively correlated with SCD5 expression in the growing tumor area." (PMID 32392704, 2020). "Specifically, we show that LINC00174 favors the expression of SYBU, FEM1B, and SCD5 genes by sponging miR-145-5p, a well-known tumor suppressor microRNA downregulated in a variety of tumors, included TETs." (PMID 33161413, 2020). "The expression of brain-specific SCD5 was also lower in the growing tumor area versus the peritumoral area and in the necrotic core versus the peritumoral area, but they were not statistically significantly for either of the reference genes." (PMID 32392704, 2020). "This analysis highlighted the involvement of SCD5 in the mechanisms responsible for tumor cell survival." (PMID 29849946, 2018). "Our previous data supported a role for the Stearoyl-CoA desaturase (SCD5) in protection against malignancy, whereby it appears to functionally modify tumor stroma impairing tumor spread." (PMID 29484133, 2018). "Given the SCD5 depletion-associated detachment of the MCF-7 cell monolayer, we sought to assess the possible influence of the enzyme in the maintenance of tumor cell viability." (PMID 29849946, 2018). "This same fatty acid has been demonstrated to inhibit tumor cell proliferation, suggesting a potential mechanistic link through which SCD5 may influence cell growth." (PMID 41463832, 2025). "In summary, we identify a novel regulatory function of VHL in relation to SCD5 and fatty acid metabolism, and propose a new mechanism of how loss of VHL may contribute to ccRCC tumor formation and progression." (PMID 36980176, 2023). "SCD5 is involved in the development and progression of different cancer types, and the induction of its gene expression by various cellular factors can contribute to tumor cell survival." (PMID 37047490, 2023). "Currently, SCD5 is primarily considered a promising type-specific tumor marker." (PMID 37047490, 2023). "However, recent findings shed light on the importance of SCD5 expression and AS in tumor progression and metastasis, and their potential as prognostic factors and predictive biomarkers for tumor therapy." (PMID 37047490, 2023). "On this basis, we evaluated if SCD5 is involved in tumor cell migration in TET." (PMID 33161413, 2020).
tumor (continued). "The influence of CAFs was also investigated on SCD5 mRNA and protein levels in tumor cells." (PMID 29849946, 2018). "Interestingly, SCD5 silencing in MCF-7 cells has revealed its involvement in the mechanisms responsible for tumor cell survival." (PMID 29849946, 2018). "Moreover, our data suggest the ability of CAFs to promote the maintenance of tumor cell survival by the induction of SCD5 levels." (PMID 29849946, 2018). "In fact, against siRNA SCD5 depletion, an induction of necrotic cell death was detected in these latter cells without affecting adhesiveness, suggesting an alternative pathway leading to tumor progression based on the CAF ability to promote cell survival through SCD5 upregulation." (PMID 29849946, 2018). "Therefore, we speculated that SCD5 might play a role in inhibiting the development and progression of tumor cells." (PMID 33903614, 2021). "The soluble form of CD5 (sCD5) can be found at low concentrations (pg/mL range) in the serum of healthy individuals, generated through proteolytic cleavage upon lymphocyte activation; sCD5 has been recently demonstrated to exert an immunomodulatory effects on experimental tumor models." (PMID 32906648, 2020). "A significant down-regulation of CD36, FABP4, PLIN1, SCD5 and ACSL4 in tumor samples has also been validated by RT-qPCR." (PMID 40860798, 2025). "Specifically, CD36, FABP4, PLIN1, SCD5 and ACSL4 were significantly downregulated in tumor samples (p < 0.05)." (PMID 40860798, 2025). "Specifically, we observed a significant down-regulation of some of the most relevant genes in the PPAR pathway (CD36, FABP4, PLIN1, PLIN4, SCD5 and ACSL4) in tumor tissue samples." (PMID 40860798, 2025). "In the growing tumor area, FADS1, FADS2, SCD, and SCD5 expression positively correlated when using the B2M gene as reference." (PMID 32392704, 2020). "The common prognostic genes between AS event and genes included KRT222, LENG8, APOB, SLC3A1, SCD5, AQP1, and ADRA1A, which played roles in tumor biology." (PMID 31140607, 2019). "Some genes, like KHNYN, HBQ1, SCD5 and FLVCR2, may play roles in tumorigenesis, metabolism or tumor therapy." (PMID 34568059, 2021). "Analysis of KEGG pathway showed that SCD5 was involved in peroxisome proliferator-activated receptor (PPAR) and AMP-activated protein kinase (AMPK) signaling pathways, which were related to the inhibition of the multiplication of tumor cell." (PMID 33903614, 2021). "In clear contrast, the genes involved in FA desaturation (stearoyl-CoA desaturase, SCD5) and PUFA trafficking (fatty acid-binding protein 7, FABP7; acyl-CoA synthetase 4, ACSL4; phospholipase A2G2D, PLA2G2D) were upregulated in tumours with PI(18:0/20:3) accumulation." (PMID 31819188, 2020). "However, when using the GAPDH gene as reference, correlations between the growing tumor area and peritumoral area were found only for SCD and SCD5." (PMID 32392704, 2020). "Therefore, the aim of this study was to analyze the mRNA expression of desaturase genes—SCD, SCD5, FADS1, FADS2, and FADS3—in GBM in three tumor zones: necrotic core, growing tumor area, and peritumoral area." (PMID 32392704, 2020). "We previously shown that the intracellular retention of SPARC in tumor cells through the over-expression of SCD5, an enzyme that mediated the synthesis of monounsatured fatty acids (MUFA), suppressed tumor growth through an alteration of satured and monounsatured FA balance." (PMID 31281314, 2019). "On the contrary, SCD5 appeared not to be significantly involved in the regulation of migration of tumor cells but needed to protect them from necrotic insults." (PMID 29849946, 2018). "In contrast, DPEP1, HADH, PLIN2, SCD5, SLC44A4, and UGT8 may function to suppress tumor growth via the regulation of immune cells with antitumor activity such as resting memory CD4 T cells, resting NK cells, M2 macrophages, resting and activated DCs, and resting mast cells." (PMID 38090559, 2023).
tumor (continued). "Results showed that some of the most relevant pathway’s regulators and effectors (CD36, FABP4, PLIN1, PLIN4, SCD5 and ACSL6) showed significantly lower expression in tumor tissue samples (p.adjusted < 0.01, data not shown)." (PMID 40860798, 2025). "A similar phenomenon was also described in human tumor cell lines, where, in contrast to SCD1, neither the change in the serum lipid level nor the presence of retinoic acid affected the expression of the SCD5 gene." (PMID 36292669, 2022).
cancer (26 papers, 2012 to 2026). A tumor composed of atypical neoplastic, often pleomorphic cells that invade other tissues. "SCD5 promotes cell differentiation of melanoma cells and its expression is associated with less malignant tumors." (PMID 31936134, 2020). "All of these microRNA families were closely associated with cancers. scd5 gene was mainly expressed in brain and pancreas." (PMID 24312911, 2013). "Interestingly, SCD5 is involved in neuronal cell proliferation and differentiation and in survival of MCF-7 cells, in which cancer-associated fibroblasts induced the expression of SCD5." (PMID 31796987, 2020). "Studies that more comprehensively address the role of SCD5 in cell- and tissue-specific cancers are needed, to gain insight into the involvement of SCD5 in metabolism and tumorigenesis." (PMID 36980176, 2023). "A growing body of evidence indicates that decreased SCD5 activity is specific to some types of cancer, and correlates with their aggressiveness and poor patient prognosis." (PMID 36980176, 2023). "While, different mRNA expression profiles of SCD1 and SCD5 were observed in the majority of cancer types." (PMID 33903614, 2021). "Collectively, the analysis showed that SCD5 had different mRNA expression profiles in different cancer types." (PMID 33903614, 2021). "The activity of SCD5 is also correlated with the activity of multiple cancer pathways such as AKT, WNT, and EGFR." (PMID 33029112, 2020). "The proto-oncogene c-myc is overexpressed in the majority of human cancers, while increased expression of SCD-1, and to a lesser extent SCD-5, has also been found in many solid tumors and associated with poor prognosis of survival." (PMID 28452935, 2017). "SCD5 plays context-dependent roles in various human cancers." (PMID 42285304, 2026). "An analysis of samples from public databases showed that SCD5 expression in different cancers could be either upregulated or downregulated." (PMID 37373069, 2023). "The SCD5 splicing event that is in the focus of our study has been identified previously as a significant prognostic marker of malignancy, treatment response and metastasis in cancer." (PMID 37047490, 2023). "Samples from TCGA were performed to carry out the survival map of SCD1 and SCD5 in human cancers." (PMID 33903614, 2021). "Though displaying similar desaturation activities, the biological role of SCD5 in human cancers remains unclear." (PMID 33903614, 2021). "Previous studies on the role of SCD5 in human cancers drew different conclusions." (PMID 33903614, 2021). "The results showed that SCD5 had different prognostic values in different cancer types." (PMID 33903614, 2021). "Altogether these data indicate that both genes could contribute to increase phenotype of cancer and as LINC00174’s role in cancer might be mediated by action of miR-145-5p on target genes, involved in different cellular pathway, as SCD5." (PMID 33161413, 2020). "SCD5 is an enzyme that is specific to the brain, with a well-known anti-cancer effect." (PMID 32392704, 2020). "Cancer-associated fibroblasts induced upregulation of the SCD5 isoform in co-cultured MCF-7 cells, with no influence on E-cadherin expression or migration ability." (PMID 31284458, 2019). "However, studies on SCD5 expression in cancer drew different conclusions." (PMID 37373069, 2023). "In some cancer types, such as DLBC, HNSC, LUSC, UCS, THCA, THYM and LGG, both SCD1 and SCD5 mRNA expression were upregulated." (PMID 33903614, 2021). "We then used integrated samples from TCGA and GTEx to identify SCD5 mRNA expression in human cancers, and compared expression differences of SCD5 and SCD1 among different human cancers." (PMID 33903614, 2021). "If it turns out that SCD5 also disrupts signal transmission from EGFR in GBM, this would indicate its anti-cancer properties, since this receptor is essential for the induction of GBM cell proliferation." (PMID 32392704, 2020).
cancer (continued). "In addition, our data observed that SCD5 was significantly involved in AMPK signaling pathway, which was related to cancer drug resistance." (PMID 33903614, 2021). "Different from SCD5, SCD1 mRNA expression was upregulated across most human cancer types." (PMID 33903614, 2021). "Conversely, SCD5 seemed not involved in the regulation of cancer cell motility." (PMID 29849946, 2018). "However, SCD5 expression and activity may not be prominent in most cancer cells." (PMID 32641978, 2020).
SCD5 also shares sentences with these, for which no sentence is quoted: infection (35 papers); HIV-1 infection (16); viral infection (5); Hepatic steatosis (4); rheumatoid arthritis (4); AIDS (3); Alzheimer disease (2); hepatic carcinoma (2); leukaemia (2); lung adenocarcinoma (2); lymph node metastasis (2); lymphoma (2); metabolic disease (2); multiple sclerosis (2); steatosis (2); systemic inflammatory response syndrome (2); adenocarcinoma (1); age-related macular degeneration (1); ankylosing spondylitis (1); atherosclerosis (1); Autoimmunity (1); breast tumors (1); cardiac hypertrophy (1); cardiovascular disorder (1); central nervous system diseases (1); chronic kidney disease (1); Cirrhosis (1); colitis (1); dermatitis (1); diabetic cardiomyopathies (1).
A further 31 diseases each share a sentence with SCD5 in 1 paper.